TNF (tumor necrosis factor)
Diseases named in the same sentence as TNF in open-access papers (continued):
Sharing a sentence is not in itself a finding about the gene and the disease.
endotoxemia (continued). "Melatonin has been shown to improve hemodynamics in rats with endotoxemia by scavenging TNF-α in the plasma, nitric oxide synthase in the liver, and oxygen free radicals in the aorta." (PMID 37205094, 2023). "We correlated the NE voltammetry signal with the anti-inflammatory effect of splenic nerve stimulation (SpNS) in a model of lipopolysaccharide- (LPS) induced endotoxemia, quantified as suppression of TNF release." (PMID 37848937, 2023). "Polyphemusins inhibit the production of pro-inflammatory cytokines TNF-α and IL-6 through LPS-stimulated macrophages, protect mice from endotoxemia, and block the development of endotoxin shock in an animal model." (PMID 37999405, 2023). "Transient endotoxemia in healthy adults increased the plasma level of TNF-α, an early response cytokine, for the first 2–3 h after bolus infusion and before gradually decreasing." (PMID 38040923, 2023). "Auricular acupuncture and electroacupuncture “Zusanli” (ST36) inhibited the expression of the pro-inflammatory factors TNF-α and IL-6 in rat models of endotoxemia through the cholinergic anti-inflammatory pathway." (PMID 36299906, 2022). "Compound 36, a potent dual PDE4/7 inhibitor and TRPA1 antagonist, exerted strong anti-TNF-α activity in vivo in lipopolysaccharide (LPS)-induced endotoxemia, which was manifested by a significant reduction in the maximum plasma concentration of TNF-α by 90.2%." (PMID 35930193, 2022). "Compound 36, a potent dual PDE4/7 inhibitor, exerted strong anti-TNF-α activity in vivo, which was manifested by a significant reduction in the maximum plasma concentration of TNF-α by 90.2% in LPS-induced endotoxemia in rats." (PMID 35930193, 2022). "We revealed the protective action of the CRG/Ech complex during endotoxemia, exhibited by a decrease in TNF-α levels in the mouse serum." (PMID 36233004, 2022). "In contrast to laboratory mice, wildling mice treated with an anti-TNFα antibody displayed a lower survival rate in a lethal endotoxemia setting than wildling mice administered with an isotype-matched control antibody." (PMID 35903109, 2022). "Data from this study demonstrate that TNF-α is the major cytokine in mediating the development of systemic inflammation and lung injury in the early phase of endotoxemia." (PMID 35337084, 2022). "They found that parasympathetic nervous system activity affects circulating tumor necrosis factor (TNF) concentrations and shock response to endotoxemia, a so-called “cholinergic anti-inflammatory pathway”." (PMID 36299906, 2022). "It has been found in animal models that clopidogrel can also reduce the levels of pro-inflammatory factors such as TNF-α, IL-6, and chemokines in endotoxemia in brain." (PMID 35659067, 2022). "It has also been shown that acute inflammation, specifically TNF production, is a driver of endotoxemia in GF mice." (PMID 36264059, 2022). "In conclusion, our results showed that treatment with Greek arbutus, chestnut, and fir honeys resulted in the suppression of inflammatory responses in mice with acute endotoxemia by reducing the production of TNF-α and iNOS." (PMID 36557628, 2022). "With the novel peptide KCF18, this study managed to achieve simultaneous inhibitions of TNF-α, IL-1β, and IL-6 and thus can compare the therapeutic effects of triple versus single cytokine inhibitions against endotoxemia." (PMID 35337084, 2022). "In a porcine model of endotoxemia, the use of hydrocortisone together with iNO reduced NF-κB and TNF and tissue injury in the lungs, kidney, and liver." (PMID 35566768, 2022). "TNF-α and IL-1β, majorly secreted by macrophages, were recognized as essential initiators in endotoxemia shock." (PMID 35252164, 2022). "Collectively, these data support the concept that TNF-α should be the major cytokine in mediating the development of lung injury in the early phase of endotoxemia." (PMID 35337084, 2022).
endotoxemia (continued). "We examined the influence of CRG, Ech, and CRG/ECh on the in vivo production of anti-inflammatory and proinflammatory cytokines (IL-10 and TNF-α, respectively) in an experimental endotoxemia model induced by LPS." (PMID 36233004, 2022). "Monocytes and macrophages produce large amounts of proinflammatory mediators, such as TNF-α and IL-6, and then lead to endotoxemia." (PMID 36532445, 2022). "The preventive administration of the CRG/Ech complex to mice prevented endotoxin-induced damage in the mouse model of endotoxemia, increased the mice’s resistance to LPS, and prevented increases in the levels of proinflammatory cytokines (TNFα)." (PMID 36233004, 2022). "One study found that taVNS inhibited the expression of TNF-α, IL-1β, IL-6, and NF-kB p65 in endotoxemia rat serum through α7nAChR-mediated CAP." (PMID 36299906, 2022). "Mice treated with TREM-1/Fc prior to LPS-induced endotoxemia had decreased serum TNF-α and IL-1β and recruitment of peritoneal neutrophils and macrophages." (PMID 35784361, 2022). "On the other hand, electrical stimulation of the vagus nerve inhibited synthesis of TNF-α in the liver, spleen and heart, and attenuated serum concentration of TNF during endotoxemia by means of the so-called “cholinergic anti-inflammation pathway”." (PMID 35530034, 2022). "As a result, Enterobacteriaceae decreased in the LGG group, the relative abundance of Clostridiales Incertae Sedis XIV and Lachnospiraceae increased, and endotoxemia and TNF-α decreased." (PMID 36012266, 2022). "Gelam honey also improved survival and inhibited the production of pro-inflammatory cytokines (TNF-a and IL-1β) and oxidative stress in an in vivo model of LPS-induced endotoxemia in rats." (PMID 36557628, 2022). "It was selected for the further in vitro and in vivo assessment based on its high inhibitory activity against PDE4 and PDE7 tested in vitro, and a profound TNFα-inhibitory potency assessed in a rat model of LPS-induced endotoxemia." (PMID 35631676, 2022). "We quantitated IL-1β, TNF-α, and IL-6 as examples of cytokines which are widely accepted as pro-inflammatory ones in many diseases, including endotoxemia." (PMID 36615318, 2022). "LPS-stimulated endotoxemia is mediated by Toll-like receptor-4 (TLR-4), which causes overwhelming production of tissue-damaging cytokines tumor necrosis factor-α (TNF-α), interleukin-1 (IL-1), and interleukin-6 (IL-6) and free radicals." (PMID 33875135, 2021). "The observation here that VNS reduced small intestinal inflammation for up to 48 h aligns with our previous finding that VNS reduced systemic TNF release in endotoxemia for up to 48 h and offers support for refining therapeutic stimulation protocols." (PMID 35095387, 2021). "In doing so, it blocks lipopolysaccharide (LPS)-induced inflammatory mediators such as tumor necrosis factor (TNF)-α and IL-6 in vitro (both in murine macrophages and human peripheral blood monocytes-hPBMC) and reduces endotoxemia, in vivo." (PMID 33806560, 2021). "Endotoxin stimulates Kupffer cell proliferation and releases a large amount of TNF-α, which not only directly damages liver cells, but also reduces the ability of the liver to clear endotoxin and aggravate endotoxemia." (PMID 33431796, 2021). "Alcohol and corticosterone-induced endotoxemia were accompanied by a synergistic elevation of plasma TNFα, IL-1β, IL-6, and MCP1." (PMID 33436875, 2021). "This late appearance of circulating HMGB1 paralleled with the onset of animal lethality from endotoxemia, and distinguished itself from TNF and other early proinflammatory cytokines." (PMID 34571869, 2021). "For example, glibenclamide significantly suppresses LPS-induced plasma IL-6 and TNF-α levels in ex vivo endotoxemia mice." (PMID 34776934, 2021). "Endotoxemia increases circulating IL-1, IL-6 and TNF-a, and these cytokines acutely and transiently activate HPA, thus, increase the release of cortisol." (PMID 34493028, 2021).
endotoxemia (continued). "Mohler KM, Torrance DS, Smith CA, Goodwin RG, Stremler KE, Fung VP, Madani H, Widmer MB, Soluble tumor necrosis factor (TNF) receptors are effective therapeutic agents in lethal endotoxemia and function simultaneously as both TNF carriers and TNF antagonists." (PMID 33909773, 2021). "Endotoxemia-activated tumor necrosis factor (TNFα)/nuclear factor kappa B (NFκB) signals result in acute on chronic inflammation-driven renal dysfunction in advanced cirrhosis." (PMID 34831270, 2021). "In the murine endotoxemia model, muscarinic receptor-mediated cholinergic signaling in the forebrain regulates peripheral immune function and inflammation to suppress serum TNF-α levels." (PMID 33936095, 2021). "Specifically, Pro9-3 effectively reduced the serum levels of the inflammatory cytokines TNF-α and IL-6 by 54.5% and 39.4%, respectively, in the LPS-induced endotoxemia mouse model." (PMID 33263333, 2021). "nNOS is a regulator of intracellular calcium in the heart and inhibits LPS-induced TNF-α improving cardiac function in endotoxemia." (PMID 33748496, 2021). "In patients with endotoxemia, which is followed by increased plasma IL-6 and TNF-alpha levels, plasma YKL-40 increased earlier than serum CRP, which is a nonspecific acute-phase protein synthesized in the liver in response to stimulation, mainly from IL6." (PMID 34579512, 2021). "The contribution of TNF-α to renal damage was confirmed using TNFR1−/− in endotoxemia, which prevents inflammation and apoptosis." (PMID 34769064, 2021). "Zn supplementation prevented the release of TNF-α and IL-1β, alleviated intestinal permeability and endotoxemia, reduced bacterial translocation, and inhibited changes in pathogenic intestinal flora in rats with SAP." (PMID 34400875, 2021). "In order to explore the functions of inulin in inflammation and endotoxemia in KO mice, the levels of LPS and inflammatory cytokines, such as TNF-α, IL-6 and IL-1β, were detected." (PMID 33104864, 2021). "Hepatocytes produced a very small amount of TNFα during the late stage of endotoxemia, but TNFα can be released by the cellular elements of blood and reach the cell surface of hepatocytes." (PMID 33471430, 2021). "For instance, we recently developed a novel peptide-based anti-TNF-α therapy against endotoxemia and confirmed its therapeutic effects." (PMID 34065201, 2021). "In cirrhosis, endotoxemia-activated tumor necrosis factor α (TNFα)/NFκB signals are involved in the development of systemic, pulmonary, splanchnic and renal dysfunction." (PMID 34831270, 2021). "In endotoxemia, the peak of early pro-inflammatory cytokines such as TNF-α is reported to occur at 60 to 90 min post-LPS administration." (PMID 33466819, 2021). "In lipopolysaccharide-induced endotoxemia, the spleen has been verified to be the major source of circulating TNF-α." (PMID 34975827, 2021). "Endotoxemia, a classical model of systemic inflammation, is characterized by the amplified production of tumor necrosis factor alpha (TNF-α), interleukin-1β (IL-1β), interleukin-6 (IL-6), and nitric oxide (NO) by immune cells and vascular endothelium." (PMID 33430014, 2021). "Neutralizing antibodies against endotoxin or early cytokines (e.g., TNF) were protective in an animal model of lethal endotoxemia, but unfortunately failed in clinical trials." (PMID 34571869, 2021). "In conclusion, the KCF18 peptide–based simultaneous inhibition of TNF-α, IL-1β, and IL-6 can alleviate liver injury in mice with endotoxemia." (PMID 34065201, 2021). "Our previous results showed that simvastatin dose-dependently decreased overproduction of TNF-α and IL-1β in endotoxemia, therefore it is conceivable that in this study, simvastatin targets both inflammatory pathways to protect renal tubules against LPS." (PMID 33008033, 2020). "We have demonstrated that tumor necrosis factor alpha (TNFα) is necessary for initiating acute neuroinflammation after endotoxemia." (PMID 32070376, 2020).
endotoxemia (continued). "Vagus nerve stimulation releases acetylcholine, which acts on the α7nAChR, to inhibit NF-κB signaling and prevent TNF-α production during endotoxemia." (PMID 33126860, 2020). "This peptide combined to several unrelated antibiotics neutralize the serum levels of TNF-α to control endotoxemia induced by bacterial infection in mice." (PMID 33505393, 2020). "The levels of IL-1β, IL-6, and TNF-α in the sera detected by ELISA and the mRNA levels in the cortices detected by qPCR increased dramatically in the endotoxemia mice." (PMID 33192176, 2020). "Direct electrical stimulation of the peripheral vagus nerve in vivo during lethal endotoxemia in rats inhibited TNFα synthesis in the liver, attenuated peak serum TNFα amounts and prevented the development of shock." (PMID 32708472, 2020). "Here, our results show that blockade of BAFF activity suppresses systemic and local inflammation, characterized by decreased serum and intestinal IL-1β, IL-6, and TNF-α levels, in LPS-induced endotoxemia." (PMID 33324396, 2020). "Additional studies using iron chelation in endotoxemia models also showed a decrease in LPS-induced activation of NF-κB and reduced plasma levels of TNF-α, IL-6, IL-1β and IL-10." (PMID 32466384, 2020). "Biomarkers of endotoxemia ((lipopolysaccharide (LPS)), inflammation (tumor necrosis factor-α (TNF-α)) and oxidative stress (8,12-iso-Isoprostane F-2alpha-VI) were measured in 16 blood samples." (PMID 32469966, 2020). "Stimulation of the central localized M1 and M2 receptors resulted in a decrease of TNFα level in blood in an endotoxemia model." (PMID 32481512, 2020). "So, this finding agrees well with the effects of SM on the production of IL-6 and TNF-α observed in the LPS-induced endotoxemia model." (PMID 33114200, 2020). "The levels of TNF-α and IL-6 were also inhibited by insulin treatment in a LPS induced murine endotoxemia model." (PMID 33679687, 2020). "In 2000, Tracey and colleagues demonstrated that efferent vagus nerve stimulation reduced TNF-α synthesis and septic shock in lipopolysaccharide (LPS)-induced endotoxemia mice." (PMID 33150250, 2020). "Firstly, we measured the serum levels of IL-6, TNF-α, and IL-1β to confirm the successful establishment of the endotoxemia model." (PMID 32894042, 2020). "Recently, a decrease in oxidative stress and a reduction in gut mucosal TNFα levels were also demonstrated by feeding a murine model of endotoxemia a high-fiber diet." (PMID 32050688, 2020). "This suggests that vagus nerve stimulation requires ChAT-expressing CD4-positive T cells to reduce TNF-α in endotoxemia." (PMID 33150250, 2020). "Stimulation of efferent vagus nerve can inhibit systemic inflammation, as demonstrated in a study that the level of TNFα in serum and liver decreased significantly in Lewis rats with endotoxemia after cervical vagotomy by electric stimulation." (PMID 33597946, 2020). "Administration of this molecule in the brain suppresses serum TNF (TNF-α) in murine endotoxemia and this effect is abrogated by surgical transection of the vagus nerve (vagotomy)." (PMID 31024522, 2019). "As a consequence, the NK compartment potentially produced reduced levels of IFNγ which was shown to strongly potentiate TNF production and mortality during experimental endotoxemia." (PMID 31849939, 2019). "Fibrinolysis is regulated by TNF-α in human endotoxemia: reduction or inhibition of TNF-α results in a shutdown of fibrinolysis." (PMID 31366975, 2019). "We observed a similar pattern of TNF‐α response in the fetus and newborn, suggesting both share the same proinflammatory pathway during the acute phase of endotoxemia." (PMID 30785235, 2019). "The results of the present study demonstrated that animals exposed to endotoxemia in the neonatal period presented with increased levels of cytokines, TNF-α, and IL-1β in the hippocampus and cortex at 60 days old." (PMID 31467920, 2019).
endotoxemia (continued). "The results also confirmed alteration of gut barrier in HFD-fed mice following endotoxemia and low-grade inflammation marked by increased serum TNF-α, and treatment with IgA21 restored the damaged barrier." (PMID 31178854, 2019). "Forebrain-selective genetic ablation of acetylcholine release and vagotomy abolished the suppression of serum TNF by the centrally-acting cholinergic drug galantamine in murine endotoxemia." (PMID 31024522, 2019). "Vagus nerve stimulation (VNS) has been shown to reduce in vivo cytokine production during endotoxemia in rat and mouse models, including a significant reduction of tumor necrosis factor (TNF), interleukin-1 (IL-1) and other inflammatory cytokines." (PMID 30862842, 2019). "Reductions in endotoxemia, TNF, and improvement in dysbiosis demonstrated by beneficial changes in the stool microbial profile have also been reported in subjects who were taking the probiotic Lactobacillus GG." (PMID 31390762, 2019). "Beutler and colleagues showed that neutralizing antibodies against TNF protected the animals against TNF-mediated endotoxemia." (PMID 30941119, 2019). "Together, these findings indicate that splenic U/S stimulation attenuates TNF production during endotoxemia through CAP and provide further evidence of a neuromodulatory mechanism versus a direct ultrasound effect on splenic immune cells." (PMID 30862827, 2019). "To explore the role of ouabain in LPS-induced endotoxemia, we analyzed the production of inflammatory cytokines including TNF-α and IL-6 in C57BL/6 mice." (PMID 31182997, 2019). "Endotoxemia induces the production of various inflammatory cytokines such as tumor necrosis factor (TNF-α) and interleukin-1ß (IL-1β) as well as reactive oxygen species (ROS)." (PMID 30810621, 2019). "MCP-1, TNF-α and IL-6 are potent drivers of immune cell infiltration in mice undergoing endotoxemia." (PMID 31072913, 2019). "Macrophages are a major source of TNF production during endotoxemia, and α7nAChR expressed on macrophages plays a critical role in mediating cholinergic anti-inflammatory signaling." (PMID 30862827, 2019). "Collectively, these data indicate that acetylcholine derived from cholinergic neurons in forebrain plays a role in mediating the suppressive effect of galantamine on peripheral TNF levels in a vagus nerve-dependent manner during murine endotoxemia." (PMID 31024522, 2019). "We previously reported that electrical vagal stimulation attenuates serum TNF levels in endotoxemia by activating the adrenal medulla to produce dopamine." (PMID 29780390, 2018). "It alleviated tumor necrosis factor-α (TNF-α) and interleukin-6 (IL-6) in activated macrophages by downregulating the NF-κB activity, and it reduced the mortality rate in LPS induced endotoxemia mice." (PMID 30297806, 2018). "We previously observed that a single pulse, equivalent to 0.1 s stimulation, is sufficient to significantly reduce TNF release in experimental endotoxemia." (PMID 30538698, 2018). "We previously reported that electrical stimulation of the vagus nerve attenuates serum TNF levels in endotoxemia by activating the adrenal medulla to produce dopamine." (PMID 29780390, 2018). "In the inflamed intestinal epithelium, TNFα produced from infiltrated immune cells further results in systemic/portal inflammation and endotoxemia." (PMID 29684027, 2018). "Here, we observed that electrical vagus nerve stimulation with a duration of 0.1–60 s significantly reduced systemic TNF release in experimental endotoxemia." (PMID 30538698, 2018). "Together, these results suggest that a short activation of the inflammatory reflex reduces TNF production during endotoxemia for ≥24 h." (PMID 30538698, 2018). "Increased bacterial translocation as indicated by endotoxemia and systemic TNF-alpha indicated either impairment or damage of the small intestine over the course of liver fibrogenesis." (PMID 30564133, 2018).